XBP1 (X-box binding protein 1)
Diseases named in the same sentence as XBP1 in open-access papers (continued):
Sharing a sentence is not in itself a finding about the gene and the disease.
cancer (continued). "While our present study is focused on elucidating the role of IRE1α/XBP1 signaling in cachectic muscle, the UPR pathways are also known to regulate tumorigenesis, cancer progression, and resistance to chemotherapeutic drugs." (PMID 40655023, 2025). "Taken together, we found that HDACi synergize with Gem in eliciting ER-stress and activating all three major UPR branches in PDAC cancer cells, with a preference for the PERK/ATF4 and IRE1/XBP1 arms and with a weaker activation of the ATF6 arm." (PMID 40287668, 2025). "However, the role of XBP1 in OvCa cells in cancer biology remains largely unknown." (PMID 40105652, 2025). "Glucosylceramide, derived from cancer cells, induces unconventional UPR in macrophages by altering lipid composition and saturation on ER membranes, activating IRE1‐mediated splicing XBP1 production and STAT member 3 (STAT3) activation." (PMID 40547943, 2025). "Simultaneously, in cancer cells, chronic activation of the UPR via XBP1 supports immune evasion through cholesterol synthesis and secretion." (PMID 39941865, 2025). "Research from the field of cancer has shown that elevated cholesterol levels induce CD8+ T cell exhaustion, as evidenced by PD-1 expression, through ER stress-XBP1-dependent mechanism." (PMID 38586464, 2024). "Cancer-related genes such as CXCR4, MMP7, CDC20 and CDK6, and unfolded protein response (UPR)-related genes such as ATF3, ATF4, XBP1 and CHOP, showed significant differences in expression in the indicated cells." (PMID 38263248, 2024). "Using the online tool GEPIA, we subsequently screened out four transcription factors (ETV4, FOXP3, E2F1 and XBP1) which are highly expressed in CRC and closely related to cancer." (PMID 38041531, 2024). "miR-3184-5p has been shown to bind X-box binding protein 1 (XBP-1), a potential transcription activator of STAT3 that plays a critical role in cancer transformation and carcinogenesis." (PMID 37514090, 2023). "We identified a spirocyclic dimer, SpiD7, and evaluated its effects on UPR activation signals, that is, XBP1 splicing, phosphorylation of eIF2α, and a decrease in ATF 6 levels, in normal and cancer cells, which were further confirmed by RNA-Seq analyses." (PMID 35378132, 2022). "Cancer cells alleviate ER-stress by activating UPR characterized by the expression of BiP, XBP1-s, CHOP, and ATF4." (PMID 35436985, 2022). "Cancer cells that are chronically exposed to multiple environmental stressors are known to overexpress IRE1 and XBP1 factors so as to shift the balance from pro-apoptotic toward pro-survival downstream pathways." (PMID 35626128, 2022). "Increased expression of Beclin-1, XBP1, CHOP, and LC3II in cancer cells suggested the AgNPs-induced mitophagy in cancer cells." (PMID 36365094, 2022). "The ERS, mediated by three conservative pathways: IRE1a‐XBP‐1, PERK‐eIF2a, and ATF6, plays a key role in cancer development." (PMID 35390056, 2022). "We found that the transcriptomic factor (XBP1) was the top-ranked in both macrophages and naïve CD4 + T cells in cancer." (PMID 36221095, 2022). "ATF6, XBP1, and CHOP were identified as core proteins in UPR signaling, which contribute to various physiological processes and cancer development." (PMID 35222510, 2021). "This seems to be the case for ERK5 inhibition of cancer cells, since it resulted in CHOP overexpression and XBP-1 splicing after 24 h, and in increased apoptosis." (PMID 34805151, 2021). "One notable example reports that Myc‐overexpressing cancer cells require SCD1 for sustained growth, which is regulated by IRE1/XBP1 signalling, thus linking UPR, lipid metabolism and cancer." (PMID 33398919, 2021). "We reasoned that survival would constitute an optimal initial readout for the complex interactions between cancer cells and immune cells in the TME with focus on the IRE1α-XBP1 axis in myeloid cells." (PMID 32520957, 2020).
cancer (continued). "To confirm that 4μ8c (30 μM) was effective, we measured Xbp-1 splicing in C57Bl/6 BMDM and B16.F10 cells treated with the CM of ER stressed cancer cells (transmissible ER stress CM [TERS CM])." (PMID 32520957, 2020). "Engrafting both LX2-stellate cells and HepG2-cancer cells led to a significant increase of collagen staining and mRNA-expression of collagen, HSPA5, and spliced XBP1 compared to scaffolds that were only engrafted with LX2-cells." (PMID 33103995, 2020). "Despite recent efforts to investigate the RIDD branch, XBP1 remains the most described target of IRE1 and thus the most studied in cancer, so far." (PMID 32111004, 2020). "PRKCSH expression was positively correlated with the expression of XBP1 target genes such as ER chaperones and ERAD components in various cancer tissues." (PMID 31320625, 2019). "Interestingly, XBP1 negatively regulates transcription of Fbw7 via a feedback mechanism through NF-κB/E2F-1 axis signaling pathway, suggesting that overexpression of XBP1s may contribute to low level of Fbw7 expression in human cancers." (PMID 30783083, 2019). "XBP1 and MYC, both known promoters of tumorigenicity and cancer progression in diverse cancer forms, were predicted as activated." (PMID 30419021, 2018). "In fact, proteins related to UPR such as GRP78/BiP, XBP1, IRE1 were reported to be promoted in ischemic regions of cancer." (PMID 30081573, 2018). "IRE1/XBP1 has been shown to confer resistance to doxorubicin and paclitaxel in TNBC and to tamoxifen in ESR1+ cancers." (PMID 30248920, 2018). "Recent studies have shown that spliced XBP1, a major component of the IRE1 pathway, promotes cancer cell survival by forming a transcriptional complex around hypoxia-inducible factor-1 (HIF-1)." (PMID 30159133, 2018). "Low glucose levels and hypoxia in cancer cells resulted in activation of PERK and XBP1 and downstream pro survival pathways." (PMID 29415493, 2018). "Consistent with its inhibitory activity on the IRE1α-XBP1 branch of the UPR, doxorubicin displayed more potent cytotoxicity against MM cell lines than other cancer cell lines that have lower basal IRE1α-XBP1 activity." (PMID 27634301, 2016). "Recently, XBP1, as a key UPR‐inducible transcription factor, binds to the VEGF‐A promoter in response to ER stress in cancer cells." (PMID 27133203, 2016). "IRE1 mediated unconventional splicing of XBP-1 mRNA and regulation of cyclin A1 expression favors IRE1-induced cancer cell growth." (PMID 26622781, 2015). "Cleavage of BLOC1S1 occurred more slowly than XBP1 splicing, and the cleavage of BLOC1S1, or RIDD as a whole, was dispensable for the control of cancer cell viability under acute ER stress." (PMID 25870107, 2015). "In the present study, we demonstrated that Scd1 expression silencing led to induction of UPR markers (Xbp1 splicing, p-eIF2α and CHOP) and CHOP-dependent cell death in cancer cells." (PMID 21179554, 2010). "Various cancer cells in mice secrete unknown soluble factors under ER stress, upregulating the expression of UPR‐related genes like GRP78, Gadd34, CHOP, and XBP1 in bone marrow‐derived macrophages in a toll‐like receptor 4 (TLR4)‐dependent manner." (PMID 40547943, 2025). "We reveal that either enzymatic IRE1 inhibition or XBP1 knockdown fails to restrain malignant growth of certain cancer models that are nevertheless attenuated by IRE1 silencing." (PMID 40208872, 2025). "ESRRA and XBP1 are known to regulate glucose, lipid, and mitochondrial metabolism while ZBTB33 is related to cell cycle progression and they have been found to be expressed in several types of cancer." (PMID 39217365, 2024).
cancer (continued). "TLR4 signaling has been shown to lead to the accumulation of HIF-1α, a key transcriptional regulator of CAMs, and the IRE1α-XBP1 signaling axis enhances HIF-1α transcriptional activity without affecting HIF-1α protein levels in cancer cells." (PMID 36475773, 2023). "Additionally, IRE1α-XBP1 signaling is essential for NSCLC progression, and ablation of IRE1α-XBP1 signaling extends survival in vivo by eliciting adaptive anti-cancer immunity." (PMID 37491302, 2023). "XBP1, a unique basic-region leucine zipper transcription factor involved in UPR that is important for cell survival to stress stimuli, is an emerging broad-spectrum target for cancer therapy." (PMID 35543228, 2022). "So, we can infer that the transcription factor XBP1 might regulate the expression of TMED2/9/10, disturb their functions, boost immune cell infiltration, thereby promoting abnormal invasion of cancer cells and leading to poor prognosis of HNSC." (PMID 35754792, 2022). "The mRNA levels of DDIT3, pERK, and ATF3 were highly upregulated upon 6-AN treatment in H460 cancer cells; however, XBP1 was not." (PMID 34827081, 2021). "Indeed, the dual opposite outputs of IRE1 RNase activity represent a great challenge in defining the right therapy for XBP1 splicing inhibition and to promote RIDD activity, depending on the cancer type." (PMID 33842465, 2021). "We firstly found that XBP1 and NAT1 have a negative association in expression and clinicopathological significance in GBC, which is never reported in other human cancers." (PMID 32793479, 2020). "Taken together, these results suggest that activation of the HBP by chemotherapy could be a common mechanism through which cancer cells antagonize cell death and this mechanism is at least partially mediated through the AKT/XBP1 axis." (PMID 29706631, 2018). "Unlike normal cells, cancer cells demonstrate constitutive activation of the UPR system (IRE1α-XBP1) under stress conditions." (PMID 30159133, 2018). "In all the three GC datasets, the positive regulation of PPP1R1B by XBP1 was increased from normal to cancer, and the negative regulation of FKBP11 by XBP1 was strengthened." (PMID 29745833, 2018). "The IRE1α-XBP1 pathway, a key branch of the UPR, is activated in many cancers." (PMID 26934650, 2016). "The properties related to cancer verified that, if S1P/S2P in the Golgi apparatus is continuously activated, it will continuously process ATF6 and activate the synthesis of the oncoproteins XBP1 and cMYC." (PMID 25522186, 2014). "Our study extends these findings by demonstrating that the alteration of IRE1α–XBP1 signaling we identified may contribute to the dysregulation of ER chaperones and UPR components observed in cancers in part, and that necrosis may serve as a critical factor exacerbating UPR dysfunction in GBM." (PMID 41516347, 2026). "Moreover, the endoplasmic reticulum of macrophages can be induced by lipids in cancer cells to induce stress and activate STAT3 and X-box binding protein 1 (XBP1) through inositol-requiring enzyme 1 (IRE1) splicing, thus promoting the pretumor phenotype of TAMs." (PMID 39192979, 2024). "However, it is critical to note that the potential role of XBP1 in efficacy of both standard chemotherapy and evolving cancer immunotherapies was not validated in BC, the role of XBP1 in BC should be further investigated." (PMID 35543228, 2022). "Furthermore, the infiltration of XBP1+ TAMs, especially XBP1+ CD206+ (representing the XBP1 activation in TAMs), in tumors was associated with shorter DFS in CRC patients, but not XBP1+EPCAM+ (representing the XBP1 activation in cancer cells)." (PMID 34667145, 2021).
cancer (continued). "Furthermore, EMT gene expression signature has been correlated with ECM protein secretion and ATF4 expression (but not XBP1) in various cancers including breast and colon." (PMID 31064137, 2019). "In our present study, we further found that XBP1 regulate VEGF expression in cardiomyocytes, which is in a line with that XBP1 s can bind to two regions on the VEGFA promoter contributes to VEGFA expression in response to ER stress in human cancer cells and mouse embryonic fibroblasts." (PMID 26572862, 2015). "Notably, therapeutic strategies targeting the XBP1/cholesterol axis or reducing cholesterol levels in tumors decrease MDSC abundance and reinstate robust antitumor responses, underscoring the potential of this pathway as a target to improve cancer immunotherapy outcomes." (PMID 39941865, 2025). "Thus, XBP1 activation in TAMs, but not in cancer cells, might be a potential immunotherapeutic target for CRC." (PMID 34667145, 2021). "Recent studies have focused on the pathogenesis of ER stress after adaption by the UPR in several cancers, because this mechanism may be useful for developing new therapeutic strategies for targeting signaling of the UPR and inhibiting this key survival pathway, including the IRE1α-XBP1 pathway." (PMID 29581854, 2018). "Whereas in the cancer cells, the IRE1 pathway is activated in its resting state; therefore, there was no additional increase in XBP1 splicing upon SpiD7 treatment." (PMID 35378132, 2022). "Constitutive activation of IRE1α is proposed to confer a selective advantage onto cancer cells over neighbouring healthy and non-UPR activated cancer cells, with recent studies demonstrating upregulated XBP1 splicing in breast, pancreatic and ovarian cancer." (PMID 31807121, 2019). "The detailed mechanisms of actions for MYB family in cancer development involving other transcription factor partners, such as SALL2, XBP1, and POU2F1, are still not clear." (PMID 24639887, 2014).
infection (133 papers, 2007 to 2026). The state of being infected such as from the introduction of a foreign agent such as serum, vaccine, antigenic substance or organism. "IRE1-XBP1 signaling can be activated in CD8+ T cells in response to infection and XBP1 loss abrogates effector T cell differentiation." (PMID 31877732, 2019). "Similar to the case of HCV, infection with murine coronavirus mouse hepatitis virus also causes a progressive increase in XBP1 S mRNA with very little XBP1 S protein." (PMID 25875739, 2015). "Infection of C. elegans with P. aeruginosa has been reported to cause splicing of XBP1 mRNA in a p38 MAPK-dependent manner." (PMID 26083346, 2015). "Previously, we reported that the activation of innate immunity by infection with pathogenic P. aeruginosa induces ER stress, and that XBP-1 serves an essential role in protecting the host against the detrimental effects of immune activation." (PMID 22125500, 2011). "In both wild-type and Ube2g2-deficient cells, infection was accompanied by XBP1 splicing." (PMID 37164963, 2023). "To further verify whether XBP1 directly regulated the inflammatory response of FFA-treated 3T3-L1 adipocytes, we overexpressed XBP1 in 3T3-L1 adipocytes by infection of cells with adenovirus encoding mouse XBP1 (Ad-XBP1)." (PMID 31630283, 2020). "Moreover, intestinal-specific knockdown of xbp-1 leads to enhanced susceptibility to PA14 infection." (PMID 25569229, 2015). "Recently, we showed that XBP-1 is required for C. elegans larval development on pathogenic Pseudomonas aeruginosa, conferring protection to the C. elegans host against the ER stress caused by its own secretory innate immune response to infection." (PMID 22125500, 2011). "The discrepancy of XBP1 induction between these viruses might reflect the differences in infection patterns of these viruses; while HCV usually causes chronic infection, JEV and Dengue cause acute infection." (PMID 17888185, 2007). "Our results also indicate that infection with L-deficient EMCV mutants not only leads to a reduced suppression of Xbp1 mRNA splicing but may also be associated with lower levels of phosphorylated IRE1 compared to cells infected with wild-type EMCV (EMCV_wt) and the EMCV_2A variant." (PMID 40143290, 2025). "Notably, N2 and xbp-1 mutant worms exhibited even more pronounced avoidance behavior when exposed to Pseudomonas aeruginosa, whereas pmk-1 mutant worms were more susceptible to infection by this pathogen." (PMID 39235964, 2024). "Lentiviral infection was employed to modulate XBP1 expression, with pLVX-XBP1 utilized for upregulation and shXBP1 for downregulation." (PMID 41971356, 2026). "In the model organism C. elegans, XBP1 protects the host from immunopathology resulting from mounting an immune response against Pseudomonas aeruginosa, thereby promoting infection tolerance." (PMID 41218768, 2025). "A notable finding is the observation that IRE1 and XBP1 accumulated at the ER together with the viral protease/helicase NS3 suggesting that nuclear translocation of XBP1s must be impeded during infection." (PMID 41157563, 2025). "In general, the three pathways were inhibited during the early phase of the SVCV infection and only the ATF4 and XBP1 pathways were significantly activated at the end of the infection cycle." (PMID 40248709, 2025). "Consistent with our gel analysis of XBP1 RT-PCR products, infection of thapsigargin-treated cells led to increased levels of XBP1 splicing." (PMID 40005508, 2025). "Asian ZIKV inhibits the IRE1–XBP1 pathway at the early stages of infection by blocking the processing of XBP1." (PMID 39459886, 2024). "Both cores also contained orthologs of the transcription factor Xbp1, part of the unfolded protein response in D. melanogaster, a further sign of ER stress in the infection response." (PMID 38594632, 2024). "Specifically, the peak of secIgM and xbp1 expression at week 5 post-infection corresponds with the timepoint when we began measuring an increase in anti-S." (PMID 39759525, 2024).